IL6 (interleukin 6)
Diseases named in the same sentence as IL6 in open-access papers (continued):
Sharing a sentence is not in itself a finding about the gene and the disease.
cancer (continued). "Additionally, IL-6 links NF-κB to STAT3, where this axis plays a prominent role in cancer-related inflammation and other pathologies." (PMID 30563089, 2018). "Our results suggested the relationship between IL-6 and genomic alterations in HCC initiation via activating the DNA damage response and genomic instability, indicating a novel pattern to promote cancers of continuous IL-6 by inducing the genomic alterations of oncogenes." (PMID 30482241, 2018). "Although our study focuses on the TGF-β1, CAFs may also secrete a cocktail of additional pro-metastatic factors, such as IL-6 and IGF-II, to contribute to cancer progression." (PMID 29325547, 2018). "Immunofluorescence staining of IL-6 and IL-6R in GC tissues and adjacent non-cancerous gastric tissues showed that IL-6 was mainly expressed in fibroblasts, while IL-6R in both cancer cells and fibroblasts." (PMID 30158543, 2018). "Some common pro-inflammatory cytokines used to induce proliferation and invasion of cancer cells include lipopolysaccharide (LPS), epidermal growth factor (EGF), tumor necrosis factor α (TNFα), interleukin β (IL-β), interleukin 6 (IL-6) and prostaglandin E2 (PGE2)." (PMID 30603045, 2018). "In this study, we found that cancer cells could induce an M2-like macrophage characterized by up-regulation of CD163 and Arg1, and down-regulation of IL-1b and IL-6 through Nrf2 activation." (PMID 30180849, 2018). "After IL-6 was added to the M2 macrophages conditioned medium, this effect was rescued, indicating that the USP24-induced metastasis activity is due to upregulated IL-6, which can be expressed by M2 macrophages or cancer cells." (PMID 30266897, 2018). "Development of lung metastases, lung inflammation, changes in blood count, systemic inflammatory response (e.g. SAA, SAP and IL-6), as well as changes in NO- and PGI2-dependent endothelial function in the aorta, were examined 2, 4, 5 and 6 weeks following cancer cell transplantation." (PMID 29788918, 2018). "Normal adipocytes stimulate the migration and invasion of cancer cells that are estrogen receptor (ER)-negative, a process mediated via a cytoskeletal element cofilin-1 and increased IL-6 secretion in adipocytes." (PMID 28929459, 2018). "It is not surprising that level of IL-6 within the serum of various cancer patients is a key prognostic indicator for their response or disease progression." (PMID 30671025, 2018). "As such, therapeutics that specifically target the microenvironment, rather than the cancer itself, are ideal and IL-6, and its myriad of downstream signaling partners, are model targets." (PMID 30671025, 2018). "The patients with tumors showing high STAT3 expression had a significantly higher risk of both disease progression (p = 0.009) and cancer-specific mortality (p = 0.009), but not with tumors expressing S1PR1 or IL-6." (PMID 30091994, 2018). "We found that already at these early stages of progression, HER2+ cancer cells upregulated expression of Ccl2 but not Csf2, Csf1, Il1β, and Il6." (PMID 29295986, 2018). "Besides Stat3 downstream signaling, IL-6 also activates Phosphoinositide 3-kinase (PI3K)/Akt pathway, which was shown to promote cancer progression." (PMID 30224299, 2018).
cancer (continued). "Moreover, the presence of plasma H3Cit in cancer patients strongly correlated with neutrophil activation markers neutrophil elastase (NE) and myeloperoxidase (MPO), and the inflammatory cytokines interleukin-6 and -8, known to induce NETosis." (PMID 29324871, 2018). "When fibroblasts are recruited by cancer cells, CAFs exist permanently in the wound healing state while producing more matrix proteins, secreting pro-inflammatory and angiogenic factors (TGF-β, VEGF, IL-6, and SDF-1), and degrading matrix proteins by MMPs." (PMID 29881724, 2018). "Considering that ER signaling in cancer requires activation of downstream PI3K/AKT and MAPK/ERK pathways, E2 could regulate IL6 expression and phosphorylation of p38MAPK and AKT, which were inhibited by Ful treatment." (PMID 29970138, 2018). "Gene set enrichment analysis and iPathway analysis identified signaling pathways with major implications to the pathobiology of cancer (e.g. TNFα, IFN, IL6/STAT, NF-κB) that are enriched in cisplatin-resistant ALDHhighCD44high cells, when compared to control cells." (PMID 29861860, 2018). "MUC2 silencing may promote CRC metastasis by interleukin-6-induced EMT, which contributes to the invasiveness of cancer cells." (PMID 29967641, 2018). "In contrast, IL-6, IL-8 and XIAP levels were reduced in TLR4-knockdown cancer cells." (PMID 29486738, 2018). "CpdA could significantly decrease expressions of IL-6, XIAP and IL-8, as well as excreted IL-8 levels together with reduced cancer viability after PTX treatment." (PMID 29486738, 2018). "In contrast to young individuals, aged individuals have consistently elevated levels of inflammatory cytokines, especially interleukin-6 (IL-6) and tumor necrosis factor-α (TNF-α), which may induce muscle atrophy and cancer through DNA damage." (PMID 29564335, 2018). "Adipocytes co-cultured with cancer cells exhibit de-lipidation, decreased expression of adipocyte markers such as Ap2 and FABP4, increased expression of MMP11, and enhanced release of inflammation-promoting cytokines IL-6 and IL-1β." (PMID 30356678, 2018). "IL-6 expression in cancer cells seems to be initiated by IL-6 produced by the cells of the IR that through IL-6R leads to the production of IGF-1Ec isoform and to the expression of IL-6 through its canonical pathway." (PMID 30134795, 2018). "Analysis of the cell secretome revealed specific cell-type differences (MDA-MB-231 cells: increased cancer attenuator follistatin and reduced pro-inflammatory cytokines IGFBP-1, MCP-1, MIP-1α, IL-6; MCF7: increased cancer signals osteopontin, sHER-2, VEGF-A, uPA, EGF amongst others)." (PMID 30603045, 2018). "In addition, experimental evidence demonstrated that combined proinflammatory cytokines such as IL-6 and TNF-α are critical for both inflammation and cancer by activating STAT3 and the NF-κB complex." (PMID 30116149, 2018). "Immunohistochemical staining for IL6 and ERβ expression was performed on both cancer tissues and adjacent non-cancerous tissues from 289 patients." (PMID 29970138, 2018). "Collectively, these data suggest that exosomal gp130 protein could be transferred to BMDMs by cancer cell-derived exosomes and subsequently activate gp130–STAT3 signaling, thereby promoting IL-6 secretion." (PMID 29867925, 2018). "CAFs secrete IL-6, IGF, HGF, FGF, and PDGF, which promote cancer cell growth." (PMID 30487436, 2018). "A likely explanation for this lack of efficacy is the plasticity of cancer cells and their ability to clonally evolve and develop subclones that are less dependent on IL-6." (PMID 30671025, 2018). "Once activated, osteoblasts produce factors such as interleukin-6 (IL6), monocyte chemotactic protein-1 (MCP-1), vascular endothelial growth factor (VEGF) and macrophage inflammatory protein-2 (MIP-2) that sustain cancer growth and interaction with other cells in the bone microenvironment." (PMID 29760166, 2018).
cancer (continued). "The activation of such transcription factors initiates the expression of various target genes contributing to cancer progression by enhancing proliferation (IL-1, TNF-α, GM-CSF, Cyclin D1), evading apoptosis (BCL2, TRAF2, BCL3) and promoting cell invasion (IL-1, IL-6, TNF, MMPs)." (PMID 28427184, 2017). "Interestingly, other than IL-6 signaling, stemness, epithelial-mesenchymal transition (EMT) and cancer pathways were also identified." (PMID 28256535, 2017). "IL-6/STAT3 pathway has been confirmed to induce EMT and metastasis in many types of cancers." (PMID 28903339, 2017). "however, the specific mechanism of IL-6 involved in anti-cancer therapy by IFN-α was not well elucidated." (PMID 29100435, 2017). "Recombinant IL-6 and MF-CM activated STAT3 and upregulated TGF-β in cancer cells." (PMID 28819126, 2017). "The expression of IL-6 was noted in stromal cells of peri- and intra-tumoral areas rather than in the cytoplasm or the nucleus of the cancer cells." (PMID 28186964, 2017). "Consequently, IL-6-induced activation of AKT is involved in protection against apoptosis, as well as in enhanced proliferation in some cancer cells." (PMID 28903416, 2017). "While its early detection and prevention is important, salivary cytokines expression, specifically of Interleukin-8 (IL-8), Interleukin-6 (IL-6) and Tumor necrosis factor (TNF-α), does contribute to the pathogenesis of cancer and these cytokines serve as potential biomarkers." (PMID 28397778, 2017). "The roles of IL-6, GM-CSF, IFN-γ in the link of inflammation and cancer have been indicated before." (PMID 28977824, 2017). "Moreover, a combination of IL-6 secreted by CD4+ T cells and growth-induced solid stress further contributes to the regulation of cancer cell morphogenesis, EMT and acquisition of a stemness phenotype." (PMID 28846080, 2017). "Constitutive IDO expression in cancer is closely related to an autocrine IL-6 signaling loop, which could be operational also in patients treated with SBRT, as suggested by enhanced IL-6 release after treatment." (PMID 29163540, 2017). "Combination of polyI:C and anti-IL6 antibody enhanced polyI:C-suppressions of survival, oncogenicity, and metastasis of A549 and potentially other cancer cells, as long as they express sufficient but non-saturating levels of functional TLR3 protein." (PMID 28427199, 2017). "In a different in vitro model, IL-6 stimulated non-stem cancer cells of breast and prostate cancer cell lines to gain cancer stem cells properties." (PMID 28966805, 2017). "They pointed that the evaluated level of IL-6 in serum correlates with survival as paraneoplastic condition in later cancer stages independent of cancer type." (PMID 28548958, 2017). "Although not unidirectional, most of the observed differences (downregulation of proteins such as enolase 2, c-Met, mesothelin, PDGF-AA, eNOS, IL-6, and upregulation of CA125) suggested a negative impact of CDC-EVs on pathways associated with cancer." (PMID 29245929, 2017). "The present study aims to investigate the roles that TGF-β and IL-6/JAK2/STAT3 signaling play in cancer cell-MF interaction and how this interaction could influence cancer cell proliferation and disease progression in both in vitro and in vivo systems." (PMID 28819126, 2017). "The inflammatory cytokine IL-6 promotes EMT, which contributes to the invasiveness of cancer cells." (PMID 28725043, 2017). "In these models, IL6 has been shown to play a central role in the dynamic equilibrium between cancer stem cells (CSC) and non-CSC, and in the maintenance and enrichment of normal and malignant mammospheres." (PMID 28472950, 2017). "High IL‐6 levels and activation of IL‐6:STAT3 signaling has been reported to induce a cancer stem cell phenotype to nonstem cells 28, while IL‐6 trans‐signaling (through IL‐6:IL‐6R) has itself been implicated in 4T1 metastasis." (PMID 26725371, 2016).
cancer (continued). "As for cancer cell migration, senescent HPMCs stimulated this process via CXCL1 and TGF-β1 (in A2780 cultures); CXCL1, CXCL8, and fibronectin in OVCAR-3 cells; and CXCL8 and IL-6 in SKOV-3 cells." (PMID 28032864, 2016). "In this study, we identified p70S6K activation by IL-6 located downstream of the PI3K/Akt/mTOR, MAPK/ERK, and JAK/STAT3 signaling pathways, which were the most important survival pathways that promote most cancers." (PMID 27174914, 2016). "Alleviation of cancer-related symptoms by MR16-1 treatment seems to contribute to the reduction of TNF-α and IL-1β levels rather than the MR16-1 treatment having a direct impact on their levels by the blockade of IL-6 signaling." (PMID 27068103, 2016). "IL-6 mediated activation of transcription factor STAT3 (to its activated form p-STAT3) is a common oncogenic process and is one of the mechanisms through which chronic inflammation contributes to cancer development and progression." (PMID 26837852, 2016). "As the addition of rutin and hyperoside reduced both TNFα and IL6, and previous work has shown that levels of TNFα are related to levels of OPG in cancer, OPG may have decreased as a result of lower levels of TNFα and IL6." (PMID 27136576, 2016). "This allows IL-6 to have effects on non-leukocyte cells that express gp130, such as cancer cells, fibroblasts, and epithelial cells (12, –, 14)." (PMID 27129274, 2016). "In the ubiquitin-proteasome proteolytic pathway, two muscle-specific E3 ligases, MAFbx and MuRF-1, play pivotal roles in the degradation of myofibrillar and intracellular proteins, and their expression during cancer cachexia is regulated by pro-inflammatory cytokines such as TNF-α and IL-6." (PMID 27064118, 2016). "An increasing number of studies have shown that cancer cells, including GBM cells, undergo autophagy in response to hypoxia, yet it remains unknown whether hypoxia-induced IL6 is a central mediator of hypoxia-induced autophagy." (PMID 27163161, 2016). "Although TNF-α inhibition has been acknowledged as a potential strategy to prevent CAC, our study suggests that SHH inhibition to target IL-6 is another strategy to either prevent cancer or kill CSCs, which was never achieved before the current investigation." (PMID 26716648, 2016). "Although evidence of direct interaction between ERBA and IL-6/IL-6R is lacking, ERBA specifically suppressed IL-6 activities and alleviated cancer cachexia." (PMID 26840088, 2016). "This is in agreement with our results, indicating that the increase in VEGF elicited by macrophage – cancer cell paracrine interaction is secondary to increased IL-6 production in the absence of hypoxia." (PMID 27514308, 2016). "IL-6 has been suggested to play an important role in cancer metastasis, but its mechanism in HNSCC has not been fully clarified." (PMID 27174914, 2016). "While further efforts are required to resolve this dispute, differential activity of CYT-Rx20 and interleukin-6 on cancer cells can not be ruled out." (PMID 27875549, 2016). "IL-6 is also a critical survival signal in breast CSCs, and switches the dynamic equilibrium toward breast CSCs over non-stem cell like cancer cells, which leads to in vivo tumorigenesis, drug resistance, and recurrence." (PMID 27609180, 2016). "This network also includes accepted cancer markers, such as TNF, STAT3, NF-κB and IL6." (PMID 27685442, 2016). "TNF-α, IL-6, TGF-β, and IL-10 have been shown to participate in cancer initiation and progression." (PMID 27171110, 2016). "Collectively, our data support the notion that activation of the IL-6/STAT3 and inflammatory-like signaling leads to deleterious effects in normal prostate epithelial cells and tumors, leading to expansion of the cancer stem-like cell compartment and self-renewal properties." (PMID 27732936, 2016).
cancer (continued). "TAM also produce some factors, such as interleukin-6 (IL-6), tumour necrosis factor-α (TNF-α), which may activate some important signaling pathways in cancer cells and stimulate cancer metastasis." (PMID 27793010, 2016). "Moreover, neutralization of IL-6 partially reverses CAF secretome's pro-proliferative, pro-migratory and pro-invasive properties on cancer cells." (PMID 27177087, 2016). "However, the IL-6 receptor and the IL-6 transducer, gp130, were found on the surface of both HNSCC cancer cells and MSCs." (PMID 27931212, 2016). "Collectively, these findings supported the activation of the IL-6/STAT3 pathway and aggressive cancer stem-like phenotype in IL-6high/ESE3low tumors and suggested that these tumors could be targeted by therapy opposing this pathway." (PMID 27732936, 2016). "In addition to its role in cancer cells, we found that blockade of Hh signaling led to decreased production of stromal cell secreted factors (SDF-1, IL-6 and VCAM-1)." (PMID 26885608, 2016). "Among adhesion molecules, ICAM-1 is upregulated in response to a number of stimuli, and several lines of evidence have shown that, in addition to its role in leukocyte adhesion and cancer cell invasion, ICAM-1 also plays a role in IL-6-mediated OS cell motility." (PMID 27851822, 2016). "Interestingly, CHEK2 down-regulation using specific siRNA increased the expression/secretion of both cancer-promoting cytokines SDF-1 and IL-6, and transdifferentiated stromal fibroblasts to myofibroblasts." (PMID 27484185, 2016). "Immunohistochemically, the carcinoma cells were faintly or focally positive for IL-6 and negative for G-CSF." (PMID 27659803, 2016). "Stage of cancer progression at the time of the study did not seem to affect intensity of serum IL-6 levels (8.1±1.3pg/ml, 4.21±2.85 pg/ml, and 7.25±3.35 pg/ml for Stage 1 (n=3), Stage 2 (n=8) and Stage 3 (n=6), respectively; P<0.67)." (PMID 26082902, 2015). "Our model implicates high Stat3 and/or IL-6 levels in senescence-competent PCa and therefore does not contradict the general observation of high IL-6 and/or Stat3 expression in many cancers." (PMID 26198641, 2015). "We also found that IL-6 neutralization markedly diminished the up-regulation of MKI67 (4T1, 1.21 ± 0.22; CT26, 1.27 ± 0.31) and PCNA (4T1, 1.54 ± 0.9; CT26, 1.20 ± 0.46) induced by ADSCs in cancer cells." (PMID 25797257, 2015). "In conclusion, our results suggest a potential role for PCT and IL-6 in predicting cancer in non-febrile patients." (PMID 26148092, 2015). "Increasing evidence supports the involvement of both IL6 and IL8 in inducing metastasis in cancer." (PMID 25970784, 2015). "Levels of the inflammatory cytokines IL-17 and IL-6 were relatively low in lysates of control normal oral tissues and the plasma of healthy controls without oral lesions or cancer." (PMID 26120967, 2015). "On the other hand, the differences in the expression of IL-6 were not seen when normal stromal fibroblasts were stimulated with lipopolysaccharide (LPS) (a model of inflammation) and were cocultured with cancer cell lines." (PMID 26690480, 2015). "Median IL-6 level was significantly lower in the control group (0 pg/ml) than in non-febrile cancer patients with stages I-III (7.376 pg/ml) or stage IV (9.635 pg/ml) (p<0.0001)." (PMID 26148092, 2015). "When activated with IL-2, NK92 cells were found to have no/low cytotoxicity against NK sensitive cancer stem cells; however, they retained the ability to secrete high levels of regulatory cytokines IL-6 and IL-10 with no or slight secretion of IFN-γ and TNF-α." (PMID 26247631, 2015).